INS (insulin)
Diseases named in the same sentence as INS in open-access papers (continued):
Sharing a sentence is not in itself a finding about the gene and the disease.
type 1 diabetes (continued). "Next we studied if OXT and its peptide analogs could provide a protective effect against impaired insulin secretion which is known to underlie the development and progression of both T2D and type-1 diabetes (T1D)." (PMID 23700406, 2013). "Autoimmune destruction of insulin producing pancreatic β-cells is the hallmark of type I diabetes." (PMID 23383295, 2013). "The insulin (INS) region is the second most important locus associated with Type 1 Diabetes (T1D)." (PMID 22567146, 2012). "Type 1 diabetes (T1D) results from the autoimmune destruction of insulin-producing beta-cells caused by yet unknown environmental factors in genetically predisposed individuals." (PMID 22567146, 2012). "Insulin deficient type 1 diabetes exhibits increased expression of NPY and hyperphagia." (PMID 22081645, 2011). "Type 1 diabetes is caused by a deficiency of insulin secretion from β-pancreatic cells." (PMID 19887507, 2011). "However recent studies demonstrate that Leptin monotherapy improves several of the metabolic imbalances caused by insulin deficient type 1 diabetes in rodents by CNS dependent mechanism." (PMID 21687731, 2011). "Similarly, an internet-based insulin pump monitoring system was associated with improved glycaemic control in children with type 1 diabetes and telemedical care reduced the number of hypoglycemias." (PMID 21210964, 2011). "As a result, the pancreasstops supplying insulin into blood causing high blood glucose concentration.Although type 1 diabetes is occasionally called childhood, juvenile, orinsulin-dependent diabetes, it is not a metabolic disorder that emerges onlyduring a childhood but after growing up to adults." (PMID 18437199, 2008). "IAA often precedes other autoimmune markers, and this led to the hypothesis that insulin may be an auto-antigen in Type 1 diabetes, which may play a role early in the pathogenic process." (PMID 18588707, 2008). "LADA is caused by immune-mediated destruction of the insulin-producing pancreatic β-cells, similar to type 1 diabetes but typically is diagnosed in patients aged 30–40 years (the diagnosis is confirmed by blood tests for the presence of glutamic acid decarboxylase antibodies)." (PMID 17448241, 2007). "Previously, we noted that, with the exception of INS, the type 1 diabetes loci contain polymorphisms that have been associated with susceptibility to other immune-mediated diseases, such as Graves' disease (GD) and systemic lupus erythemastosus (SLE), suggesting the existence of shared disease loci." (PMID 18045485, 2007). "Type 1 Diabetes (T1D) is an autoimmune disease initiated by a culmination of both genetic and environmental; these factors result in a cascading loss of pancreatic β-cells and insulin production, promoting dysglycemia, which is recognized as the symptomatic stage of T1D." (PMID 41033431, 2026). "In type 1 diabetes mellitus (T1DM), there is destruction or dysfunction of the functional insulin-producing β-cells of the pancreas in genetically predisposed individuals." (PMID 40002565, 2025). "However, the clinical translation of our findings will require future research using a combination of in vivo and ex vivo work to understand the factors that restore normal platelet physiology and reduce the risk of thrombosis in the insulin-resistant type 1 diabetes population." (PMID 40304758, 2025). "For patients with type 1 diabetes (T1D) who choose to fast during Ramadan, as they need to re-adjust insulin doses and timing to minimize the risk of abnormal glycemic changes." (PMID 40510485, 2025). "Conversely, another study reported impaired insulin secretion despite normal exocrine function in recent-onset type 1 diabetes, suggesting that exocrine abnormalities might only affect a subset of individuals at risk of type 1 diabetes." (PMID 40295334, 2025).
type 1 diabetes (continued). "Treatment of type 1 diabetes is challenging, and individuals need to master attention-demanding tasks such as frequent blood glucose monitoring, carbohydrate counting, considering insulin dose and insulin administration in association with meals, as well as adjustments for physical activity." (PMID 41255955, 2025). "Type 1 diabetes mellitus (T1D) is a prevalent genetically predisposed disorder characterized by dysregulation of glucose metabolism and immune-mediated endocrine dysfunction, primarily resulting from insufficient insulin secretion due to autoimmune destruction of pancreatic β-cells." (PMID 40755762, 2025). "Type 1 diabetes mellitus (T1DM) is a chronic autoimmune disorder characterized by insulin deficiency, requiring lifelong management with insulin therapy." (PMID 40630348, 2025). "Type 1 diabetes mellitus (T1DM), as a chronic autoimmune disease, is characterized by the selective loss of insulin-producing beta cells (β cells) mediated by T cells." (PMID 40141192, 2025). "Consequently, individuals with type 1 diabetes are at an increased risk of hypoglycaemia and, despite significant advances in insulin therapy, hypoglycaemia remains a critical challenge in type 1 diabetes management by limiting proper glycaemic control and by contributing to morbidity and mortality." (PMID 40374968, 2025). "Type 1 diabetes (T1D) is an autoimmune disease which develops because of contributing genetic and environmental factors and leads to a defect in self-tolerance, resulting in the T-cell mediated destruction of pancreatic beta cells and a subsequent loss of insulin production." (PMID 40149976, 2025). "Type 1 diabetes (T1D) is an organ-specific autoimmune disease that results in the selective loss of pancreatic beta cells and an eventual deficit in insulin production to maintain glucose homeostasis." (PMID 40149976, 2025). "Type 1 diabetes mellitus (T1DM) is an autoimmune disease caused by the destruction of the beta cells of the pancreas responsible for making insulin." (PMID 39320093, 2024). "In this cohort study of insulin users with type 1 diabetes in Colorado, we found that state legislation capping out-of-pocket costs at $100 per prescription for a 30-day supply of insulin was associated with declines in out-of-pocket spend and increases in adherence to insulin therapy." (PMID 39141389, 2024). "Associated with the fact that the type 1 diabetes treatment regimen is associated with weight gain, and a higher BMI is related to worse metabolic control, there is a need for adjuvant therapy with insulin, which improves glycemic control and reduces insulin requirements." (PMID 38675446, 2024). "Type 1 diabetes (T1D) is an autoimmune disorder that results in the destruction of pancreatic beta cells, causing a shortage of insulin secretion." (PMID 39371824, 2024). "Exogenous insulin replacement to obtain glycemic control is a hallmark for type 1 diabetes (T1D) treatment." (PMID 38686202, 2024). "Type 1 diabetes mellitus (T1DM) is a chronic autoimmune disease caused by the destruction of pancreatic β-cells, leading to the complete cessation of insulin production." (PMID 39681809, 2024). "Human type 1 diabetes (T1D) is caused by autoimmune attack on the insulin-producing pancreatic beta cells by islet antigen-reactive T cells." (PMID 38871688, 2024). "Type 1 diabetes (T1D) is an insulin-dependent condition caused by the destruction of pancreatic β-cells, which causes insufficient insulin secretion in the body." (PMID 39398332, 2024). "Indeed, increasing insulin promotes weight accrual in humans; as demonstrated by type 1 diabetes (deficient insulin production); one of the cardinal symptoms of the disorder is weight (especially adipose tissue) loss, while insulin supplementation rapidly increases weight gain and adiposity." (PMID 38212644, 2024).
type 1 diabetes (continued). "In type 1 diabetes (T1D), tolerance to islet autoantigens is broken, causing autoimmune destruction of insulin-producing β-cells in the pancreatic islets of Langerhans by autoreactive T cells, resulting in insulin shortage and dysregulated blood glucose levels." (PMID 39596627, 2024). "Type 1 diabetes mellitus (T1DM) is an autoimmune disease characterized by an absolute deficiency of insulin secretion." (PMID 39768822, 2024). "Diabulimia describes the behavior of patients with type 1 diabetes (T1D) who deliberately administer inadequate insulin to themselves for the purpose of weight loss." (PMID 38041170, 2023). "Type 1 diabetes mellitus (T1DM) is a chronic inflammatory autoimmune disease caused by the destruction of pancreas beta cells and causing life-long dependence upon external insulin." (PMID 37568220, 2023). "Type 1 diabetes mellitus (T1DM) is an autoimmune disease that involves insufficient insulin secretion caused by the destruction of pancreatic islet β cells." (PMID 37432230, 2023). "Type 1 diabetes (T1D) is a chronic autoimmune disease featured by a progressive loss of beta cell function that requires lifetime insulin replacement." (PMID 37229215, 2023). "Psychosocial stress, such as serious life events, which has been shown to increase the risk of Type 1 Diabetes, could act either by increasing insulin demand as stress releases hormones including adrenalin and cortisol that increases blood glucose levels, or by influencing the immune balance." (PMID 37061552, 2023). "In this study, we aimed to determine which patterns of nocturnal glucose profiles are associated with NH in patients with type 1 diabetes (T1D) managed with multiple daily insulin injections." (PMID 37888065, 2023). "However, beta cell replacement—either by solid organ pancreas transplant or islet transplantation—remains the sole curative intervention for Type 1 diabetes and avoids the life-threatening complication of hypoglycemic episodes associated with intensive insulin therapy." (PMID 37359825, 2023). "Type 1 diabetes (T1D) is an autoimmune disease characterized by hyperglycemia and metabolic disorder, which is caused by the destruction of insulin-producing pancreatic β-cells and absolute insulin deficiency." (PMID 38169963, 2023). "As insulin is essential for regulating blood sugar levels in individuals with type 1 diabetes, reducing or omitting insulin leads to elevated blood sugar levels, causing the body to break down fat for energy, resulting in weight loss, which may be the desired outcome for some individuals." (PMID 37764739, 2023). "The most prevalent type of IDD is type 1 diabetes (T1D), which is an autoimmune condition that leads to specific destruction of beta cells and complete loss of insulin-production." (PMID 36978130, 2023). "Genetic variation in the insulin gene (INS) is the second largest contributor to genetic risk to type 1 diabetes (T1D)." (PMID 36701305, 2023). "Type 1 Diabetes (T1D) is an autoimmune disorder with an absolute deficiency of insulin, characterized by the destruction of pancreatic beta cells." (PMID 35509734, 2022). "Type 1 diabetes mellitus (T1DM) is a chronic condition caused by autoimmune destruction of insulin-secreting pancreatic β-cells, characterized by severe insulin deficiency." (PMID 36130979, 2022). "Type 1 diabetes mellitus (T1DM), an autoimmune disease, is caused by insulin deficiency due to destruction of the insulin-producing pancreatic beta cells." (PMID 36615856, 2022). "Type 1 diabetes (T1DM) is a disease characterized by insufficient insulin production caused by pancreatic β-cell damage." (PMID 35744996, 2022). "Type 1 diabetes (T1D) is caused by the autoimmune destruction of pancreatic beta cells that produce insulin." (PMID 35464420, 2022). "Among these diseases, neonatal diabetes mellitus (NDM) was traditionally considered a variant in Type 1 diabetes mellitus (T1DM) and had accordingly been treated with insulin." (PMID 35212627, 2022).
type 1 diabetes (continued). "Type 1 diabetes (T1D) is a chronic autoimmune disease characterized by pancreatic islet inflammation resulting in eventual specific loss of the insulin-secreting β-cells." (PMID 36289205, 2022). "Type 1 diabetes mellitus (T1DM) is an autoimmune disease associated with failure in insulin production that occurs as a consequence of the pancreatic islet β-cells dysregulation mediated by T-cells." (PMID 36506063, 2022). "Out of these, Type 1 diabetes (T1D) is caused by an autoimmune disorder that inhibits the production of insulin in affected individuals." (PMID 35336018, 2022). "Ensuring a balance of available glucose and skeletal muscle uptake can be challenging with exogenous insulin administration, which also inhibits hepatic glucose release, and there is a significant risk of hypoglycaemia, both during and after exercise, in people with type 1 diabetes." (PMID 36425473, 2022). "Insulin under-dosing, intentional vomiting, feeling of losing control over food, a short-term weight loss (over 6 kg), and body dissatisfaction are disordered eating behaviors that have been reported to be associated with type 1 diabetes in adolescents and youth." (PMID 35459205, 2022). "Consequently, islet destruction led to insulin-deficient type 1 diabetes." (PMID 35061693, 2022). "There is much evidence to demonstrate that type 1 diabetes patients, like patients with type 2 diabetes, are at a greater risk than the general population of being overweight or obese, of developing metabolic syndrome (MetS) and of developing resistance to injected insulin." (PMID 34684518, 2021). "Type 1 diabetes (T1DM) is an autoimmune disease characterized by the gradual loss of β-cell function and insulin secretion." (PMID 34959363, 2021). "Type 1 diabetes mellitus (T1DM) is a common autoimmune disease characterized by the apoptosis of β cells and absolute deficiency of insulin secretion, which leads to chronic hyperglycemia, polydipsia, ketoacidosis, and other metabolic disorder." (PMID 34095316, 2021). "The current standard treatment of Type 1 diabetes mellitus (T1DM) using subcutaneous administration of exogenous insulin is associated with daily stress and increased rate of severe hypoglycemic events due to suboptimal absorption and imprecise dosing." (PMID 34445075, 2021). "Type 1 diabetes (T1D) is a chronic disease in which the immune system attacks and destroys the pancreatic beta cells resulting in the loss of insulin secretion." (PMID 33770092, 2021). "While tweets reporting bankruptcy, stealing, and homelessness associated with the cost of insulin may seem like extreme subjects to post on a public platform, a study in 2020 with individuals with type 1 diabetes in the United States corroborated these stories." (PMID 33496671, 2021). "Type 1 diabetes (T1DM) is an autoimmune disease caused by immune-mediated destruction of insulin-producing β cells in the pancreas." (PMID 33574570, 2021). "Moreover, in individuals with type 1 diabetes exercise leads to a paradoxical increase in insulin concentrations believed to be caused by increased blood flow and absorption of subcutaneous deposits of insulin possibly contributing to the attenuated glucagon release." (PMID 34405569, 2021). "Type 1 Diabetes Mellitus (T1DM) is a chronic metabolic disease characterized by the insufficient production of endogen insulin caused by autoimmune β-cell destruction." (PMID 33572499, 2021). "Type 1 diabetes (T1D) is a chronic autoimmune disease, characterized by progressive destruction of pancreatic insulin-producing β cells in genetically at-risk individuals." (PMID 34702762, 2021). "Type 1 diabetes mellitus (T1DM) is a chronic autoimmune disease caused by a dysfunction of pancreatic beta cells with a loss of insulin secretion." (PMID 34682564, 2021). "Type 1 diabetes (T1D) is a chronic autoimmune disease that leads to the selective loss of insulin-producing β-cells by activating the T cells." (PMID 32787907, 2020).
type 1 diabetes (continued). "Type 1 diabetes (T1D) is characterised by T cell mediated autoimmune destruction of insulin-producing pancreatic β cells, causing T1D individuals to become insulin-dependent throughout their life." (PMID 33193091, 2020). "Type 1 diabetes mellitus (T1D) is a chronic immune-mediated disease characterized by the selective loss of insulin-producing-β-cells in the pancreatic islets in genetically susceptible individuals resulting in severe insulin deficiency." (PMID 32566279, 2020). "Type 1 diabetesmellitus (T1D) is caused by partial destruction of the insulin-producing beta cells in the pancreas and is a major issue for public health care worldwide." (PMID 33312173, 2020). "Enterovirus (EV) infection of insulin-producing pancreatic beta cells is associated with type 1 diabetes (T1D), but little is known about the mechanisms that lead the virus to cause a persistent infection and, possibly, to induce beta cell autoimmunity." (PMID 32664675, 2020). "Development of treatment regimens might contribute to decrease in the incidence of severe hypoglycemia; however, despite the advent of new insulin regimens, severe hypoglycemia still remained a relevant risk and a current threat for patients with type 1 diabetes and their family members." (PMID 33042005, 2020). "Type 1 diabetes (T1D) is a medical condition caused by deficient insulin production and results in dysregulation of blood glucose." (PMID 32517068, 2020). "Type 1 diabetes (T1D) is an autoimmune disorder caused by destruction of the pancreatic islet beta cells resulting in total loss of insulin production." (PMID 33033923, 2020). "Studies have shown that overnight closed-loop insulin delivery can improve glucose control and reduce the risk of hypoglycemia and hence may improve metabolic outcomes and reduce burden for children with type 1 diabetes and their families." (PMID 30849076, 2019). "Type 1 diabetes mellitus (T1DM) is an autoimmune T-cell-mediated damage to pancreatic β cells, leading to an absolute deficiency in endogenous insulin." (PMID 31849842, 2019). "Since the insulin production was suppressed in T1D mice, it hypothesized that the omentin gene expression and its serum levels rise to compensate the insulin deficiency in type 1 diabetes." (PMID 31428203, 2019). "Type 1 diabetes (T1D) is characterized by a progressive loss of beta cells and thereby insulin secretion, resulting in hyperglycaemia." (PMID 31757005, 2019). "An intense search for methods to quantify methylated and unmethylated insulin cfDNA is ongoing, as it would enable us to diagnose Type 1 Diabetes (T1D) and β-cell destruction before the loss of a significant number of insulin-producing cells." (PMID 30953560, 2019). "Type 1 diabetes (T1D) is a metabolic disease caused by the autoimmune destruction of insulin-producing β-cells." (PMID 29491866, 2018). "Type 1 diabetes mellitus (T1D) is a heterogeneous, chronic autoimmune disorder characterized by selective loss of the insulin-producing pancreatic beta cells." (PMID 30006587, 2018). "Type 1 diabetes (T1D) is an autoimmune disease in which a strong inflammatory response causes the death of insulin-producing pancreatic β-cells, while inefficient regulatory mechanisms allow that response to become chronic." (PMID 30687329, 2018). "Type 1 diabetes (T1D) is a multifactorial disease caused by autoimmune destruction of pancreatic beta cells, which results in a breakdown of insulin production and glucose metabolism." (PMID 30050502, 2018). "Type 1 diabetes mellitus (T1DM) is primarily an autoimmune disease caused by destruction of insulin producing pancreatic β-cells." (PMID 30177968, 2018). "Type 1 diabetes (T1D) results from an organ-specific autoimmune-mediated loss of insulin-secreting β cells in the pancreas." (PMID 28279194, 2017). "Type 1 diabetes mellitus (T1D) is an autoimmune disorder that causes destruction of pancreatic β cells and insulitis resulting in loss of insulin secretion." (PMID 28503574, 2017).